FAP (fibroblast activation protein alpha)
Diseases named in the same sentence as FAP in open-access papers (continued):
Sharing a sentence is not in itself a finding about the gene and the disease.
tumor (continued). "Thus, FAP‐targeting immunotherapies may be a promising therapeutic modality for an aggressive tumor type, the lethal natural history of which is only delayed by standard combination treatments." (PMID 33082953, 2020). "Both FAP and STC1 mRNA levels were increased in C2‐cocultured PF, while FAP mRNA upregulation was also detected in miR‐27a knockdown fibroblasts, confirming their activation and further supporting our hypothesis of tumour cell‐derived activation of fibroblasts." (PMID 32133790, 2020). "Moreover, adoptive transfer of FAP-targeted chimeric antigen receptor (CAR) T cells could specifically kill FAP+ CAFs and induce multiple beneficial stroma alterations, leading to delayed tumor growth and survival extension in mouse models of NSCLC and PDAC." (PMID 31417869, 2019). "The amount and distribution of FAP-expressing CAFs, as well as the number of FAP molecules per cell, may differ, resulting in different pharmacokinetic profiles for the radiotracers in different tumor types." (PMID 30850501, 2019). "The authors reported that this may have been due to the use of mouse tumor lines with limited FAP expression, while robust FAP staining by IHC was observed in multiple human tumor samples, indicating that human tumor cell lines may have been better targets for the study." (PMID 30804938, 2019). "There are many tumour-CAF co-targeting clinical trials currently recruiting patients: for example, RO6874281 is a recombinant fusion protein that targets an engineered, variant form of IL-2 to human FAP+ cells, to stimulate a local immune response and therefore improve anti-tumour immunity." (PMID 31289350, 2019). "Using this approach, the limiting factor for the detection of tumor lesions is the number of FAP-positive cells in the tumor micrenvironment i.e. the percentage of stromal content, and/or the number of FAP molecules per fibroblast which may be determined by the surrounding cells." (PMID 31659499, 2019). "Depletion of FAP-expressing stromal cells resulted in a better immunological response and a lower tumor burden,These findings may suggest therapeutics that selectively target FAP-expressing cells, but not other cancer-associated stromal cells, may result in a better prognosis." (PMID 30987642, 2019). "This suggests that αSMA and FAP fibroblasts may influence the tumor microenvironment differently." (PMID 31659499, 2019). "For example, the cancer-associated fibroblasts (CAF), which support tumor growth by secreting growth factors, chemokines, and extracellular matrix, could be destroyed by CAR-T cells targeting fibroblast activation protein (FAP), and potent antitumor effects by CAR-T-FAP have been also confirmed." (PMID 31221182, 2019). "Studies with unseparated primary tumor samples (containing tumor cells, CAFs and infiltrated immune cells) also demonstrated potent activation of the endogenous T-cells, indicating that virus produced FAP-TAC is a potent T-cell activator despite suppressive influences of the TME." (PMID 30400822, 2018). "FAP expression on TAMs could serve as a marker of a regenerative-like tumour microenvironment." (PMID 30054470, 2018). "Therefore, it went a step further to detect tumor promoting functions of stromal FAP." (PMID 30419872, 2018). "FAP-TAC constructs comprising linked ScFv antibodies specific for human FAP and CD3 were designed and used to generate EnAd viruses expressing the FAP-TAC transgene such that expression was under the virus major late promoter (MLP) to allow broad or tumor-selective expression, respectively." (PMID 30400822, 2018). "Since tumor microenvironment plays a critical role in tumor growth, evasion, and immune escape, several studies demonstrated that stromal cells in tumor microenvironment expressing FAPα are associated with chronic, non-infected inflammatory lesions." (PMID 28881756, 2017). "We hypothesized that MM-BMSCs suppress the anti-tumor immunity that is mediated by FAPα." (PMID 28881756, 2017).
tumor (continued). "As reviewed above, FAP α belongs to the serine proteinase family, has both collagenase and dipeptidase activities which can degrade gelatin, collagen, and other substrates of dipeptidase, and promotes tumor growth, migration, invasion, metastasis and ECM degradation." (PMID 26985769, 2016). "Importantly, the proteolytic activity of FAP can support tumor growth and proliferation." (PMID 27834810, 2016). "However, it has been reported that FAP can also function as a tumor suppressor." (PMID 27834810, 2016). "Therefore, it was hypothesized that selectively blocking the enzymatic activity of FAP α may be a method of targeting it in tumor development." (PMID 26985769, 2016). "In sum, these findings support the hypothesis that FAP α is a novel target for tumor therapy." (PMID 26985769, 2016). "Thus, it appears that the FAP-expressing tumor cell vaccine may achieve maximal anti-tumor effects, as it targets both CAFs and tumor cells for elimination." (PMID 26394925, 2015). "A recent study even suggested that FAP inhibition might be beneficial for treating epithelial-derived tumours, since pharmacologic targeting of FAP inhibited tumour stromagenesis by affecting integrin-mediated signalling and led to a decreased recruitment and overall number of myofibroblasts." (PMID 25852817, 2015). "Additionally, the studies demonstrated that targeting FAP expression in tumor cells may be a novel therapeutic target." (PMID 25775399, 2015). "In conclusion, FAP influences OS cells and may play a role in OS tumor progression and metastasis." (PMID 24520291, 2014). "FAP influences OS cells and may play a role in OS tumor progression and metastasis." (PMID 24520291, 2014). "However, the role of FAP in tumorigenesis and tumor growth, invasion and metastasis, as well as the exact molecular mechanisms, remain unknown." (PMID 24520291, 2014). "Moreover, neutralising antibodies against tumour necrosis factor-α or interferon-r restored tumour growth inhibition by ablating FAP+ CAFs, indicating essential roles of these fibroblasts in modulating carcinoma cell responses to the cytotoxic effects of both cytokines." (PMID 24216702, 2013). "Individual cases exhibited variations, like higher vimentin with lower FAP and PECAM1/CD31, highlighting tumor morphological heterogeneity and regional adaptability." (PMID 40694103, 2026). "By correlation analysis, a tendency (r = 0.52; p = 0,08) for a positive relationship between FAP expression and PECAM1/CD31-positive vascular tumor areas was identified." (PMID 40694103, 2026). "For example, the FAP-targeting antibody-drug conjugate OMXT705 specifically engages FAP+ CAFs and releases the cytotoxin TAM470 to kill tumor cells." (PMID 41362727, 2026). "For instance, selective depletion of FAP-α+ CAFs enhanced anti-cancer immunity by increasing CD8+ T cell infiltration, resulting in significant suppression of primary tumor growth." (PMID 41355964, 2026). "In colorectal cancer (CRC), interactions between SPP1+ macrophages and FAP+ fibroblasts, mediated by macrophage-derived factors such as TGFB1 and IL1A/B drive the development of a fibrotic barrier along the tumor margin." (PMID 41425545, 2025). "While FAP-CAR-T cells show promise in activating the immune system and eliminating target cells, concerns about on-target off-tumour toxicity due to low-level FAP expression in healthy tissues persist." (PMID 40741380, 2025). "Fibroblast activation protein-α (FAP), a membrane-bound serine protease, is one of the most studied CAF markers and plays a central role in tumor–stroma interactions." (PMID 41303595, 2025). "Lastly, the low physiological expression of FAP in the gastrointestinal tract and high specificity of the FAPI tracer for the target facilitate an improved tumour-to-background distinction." (PMID 40076605, 2025). "In NSCLC, FTO can mediate tumor progression through FTO-mediated autophagy and FAP/integrin/FAK signaling." (PMID 40722726, 2025).
tumor (continued). "PET parameters, including standardized uptake value (SUV), metabolic tumor volume (MTV), and FAP-expressing tumor volume (FTV), were evaluated for diagnostic accuracy." (PMID 40584995, 2025). "FAP is a key biomarker of CAFs involved in ECM remodeling and fibrosis, promoting tumor progression and creating an immunosuppressive TME." (PMID 40230452, 2025). "In preclinical models of PDAC, while ablation of the tumour-restrictive α-SMA+ CAFs reduced survival, depletion of FAP+ CAFs significantly improved survival and enhanced the efficacy of immune checkpoint inhibitors (ICIs)." (PMID 39780187, 2025). "Using a multi-step selection process and analysis of patient tumor tissue, we identify two antigens, MAGEA4 and FAP, as potential targets for an mRNA vaccine." (PMID 41345672, 2025). "Of note, those groups of FOXL2+COL1A1+ cells, besides positivity for COL1A1, had higher expression of αSMA, PDGFRa, and FAP (frame 2) than FOXL2+COL1A1− tumor cells themselves (frame 1)." (PMID 41042551, 2025). "Given the theranostic potential of emerging new-generation FAPI radiopharmaceuticals and the growing innovation in the field of anti-FAP pseudopeptides, the demand for PET imaging of the tumor microenvironment is expected to increase significantly." (PMID 40766056, 2025). "Another population of FAP+PDPN+ CAFs, which closely interacts with T cells at the tumor periphery, was shown to significantly suppress the proliferation of CD4+ and CD8+ T cells by secreting nitric oxide." (PMID 40890855, 2025). "These interventions predominantly focus on myCAFs and iCAFs, which are integral to tumor progression and TLS modulation, by targeting their FAP expression and cytokine-mediated pathways, respectively." (PMID 40784879, 2025). "RNA-seq analyses of tumor tissues from PDX models (Utd, FAP CAR-T, and FAP/IL-15 CAR-T groups) were conducted to profile gene expression changes." (PMID 41455698, 2025). "Differentially expressed genes such as FAP, SERPINH1, and the newly reported PSAPL1 are involved in tumor progression, extracellular matrix remodeling, and immune response modulation." (PMID 41244835, 2025). "Although FAP-PET imaging has certain limitations (e.g., overlapped uptake between tumor and benign fibrotic lesions), its noninvasive nature provides a valuable tool for both identifying suitable candidates for FAP-RLT and monitoring therapeutic response." (PMID 41425958, 2025). "Given the important role of FAP+ fibroblasts in modulating pro-tumoric signaling pathways within the PCa TME, we performed intercellular correlation analyses to uncover potential tumor-driven mechanisms." (PMID 40438108, 2025). "Preclinical studies in EC models suggest that targeting FAP (e.g., with inhibitory antibodies or small molecules) or blocking IL-6 signaling can inhibit CAF activity, reduce tumor growth, and sensitize tumors to chemotherapy." (PMID 40746533, 2025). "In parallel, CDCP1-high tumor cells condition fibroblasts toward a myofibroblastic, pro-tumor phenotype (α-SMA, FAP, PDGFRβ, S100A4 upregulation), linking a tumor-intrinsic epigenetic program to stromal reprogramming." (PMID 41301830, 2025). "Instead, we observed an upregulation of FAP expression from baseline in NCL fibroblasts, coupled with a reduction in tumour-derived fibroblasts, reinforcing the shift toward a shared phenotype." (PMID 40640541, 2025). "FAP, a membrane-bound serine protease belonging to the dipeptidyl peptidase (DPP) family, is commonly expressed by CAFs and certain tumour cells such as sarcoma." (PMID 39780187, 2025). "In immune-competent models, the elimination of FAP +ve CAFs aided in amplifying CD8+ lymphocyte infiltrate, resulting in enhanced tumour suppression." (PMID 40379112, 2025). "While H4-Fc had the best affinity for FAP of all the constructs (14pM), it had the worst EC50 values for internalization and cytotoxicity, yet it demonstrated high tumor uptake." (PMID 39868181, 2025).
tumor (continued). "In the preceding studies, the modified tumor cells expressed FAPα, promoted the infiltration of CD8+ T-cells into the stroma while simultaneously reducing immunosuppressive cells in the tumor microenvironment, including MDSCs, Tregs, and M2-macrophages." (PMID 40918451, 2025). "The FAP-α-responsive and thermosensitive liposome design (CAP-ITSL) focused chemotherapeutic administration to CAF-rich tumor stroma." (PMID 40124335, 2025). "Tumor-stroma dual-targeting BsAbs simultaneously engage TAAs and stromal or angiogenic components within the TME (e.g., FAP, VEGF)." (PMID 41476945, 2025). "Altogether, these results suggest that tumoral FAP and sFAP activity in circulation may serve as important biomarkers for disease aggressiveness, potentially reflecting the proteolytic activity within the tumor microenvironment that supports tumor growth and immune evasion." (PMID 41373408, 2025). "Distant metastasis (pM). ccRCCs with synchronous distant metastases exhibited significantly higher percentages of FAP + and CD68 + cells at the tumor periphery as well as elevated percentages of CD8 + and CD68 + cells at the tumor center." (PMID 39751643, 2025). "The heterodimeric radioligand FAPI-RGD, which simultaneously targets FAP and integrin αvβ3 (RGD), has demonstrated superior tumor uptake and retention compared to its monomeric counterparts." (PMID 41425958, 2025). "These investigations have highlighted that CAFs are activated fibroblasts typically expressing markers like FAP, FSP, and αSMA, which are important in promoting tumor growth and resulting in chemotherapy resistance." (PMID 40438108, 2025). "Examples include RG7386 (FAP/DR5), RO7300490 (FAP/CD40), and FAP-4-1BBL, which co-engages T cells to enhance CD8+ T-cell activation and promote tumor regression." (PMID 41441395, 2025). "The myCAFs were present near the tumor cells and characterized by α-SMA+, FAP+, and expression of TGF-β response genes." (PMID 40296919, 2025). "Adoptive FAP-specific chimeric antigen receptor (CAR) T-cell therapy is an innovative approach to directly target and deplete most FAP+ CAFs and to restrict tumor stroma production, resulting in antitumor effects." (PMID 40296919, 2025). "The vaccine induced FAP-specific CD8+ T-cells, leading to a reduction in the number of FAPα+ cells, immunosuppressive cells (MDSCs and Tregs), and an alteration in the tumor cytokine environment (reduction of IL-4, IL-10, TGF-β)." (PMID 40918451, 2025). "RKO tumor FFPE sections were stained with antibodies against FAP and LRRC15, along with HA-binding protein (HABP) to confirm the high levels of FAP and LRRC15 proteins in the tumor samples with a concomitant abundance of HA within the TME." (PMID 41228205, 2025). "In vivo, HE4-silenced xenografts displayed restricted tumor growth accompanied by reduced stromal expression of α-SMA, FAP, and collagen I." (PMID 41502510, 2025). "To further generalize these findings, we assessed the correlation of AEBP1 expression with CAF markers (ACTA2, FAP, and PDGFRB) and representative collagen family genes across 32 TCGA tumor types." (PMID 41373631, 2025). "The observed trend indicates that CAFs expressing FAP as well as CD68 + macrophages and tumor-infiltrating lymphocytes (TILs) (CD4, CD8, and CD4 + FOXP3 +) are more abundant in the more aggressive ccRCCs." (PMID 39751643, 2025). "FAP+ CAFs, as the primary source of CXCL12 within tumors, secrete CXCL12 that enriches on the tumor cell surface." (PMID 40890855, 2025). "FAP-targeted liposomes deliver chemotherapeutic drugs (e.g., paclitaxel) to inhibit CAF secretion of tumor-promoting factors." (PMID 40094065, 2025). "Another bispecific antibody, targeting both FAP and DR5, displayed strong anti-tumour efficacy in preclinical models and is currently under clinical evaluation." (PMID 39780187, 2025).
tumor (continued). "The released DOX acts on both tumor cells and CAFs, significantly reducing expression of CAF markers (α-SMA, FAP-α, TGF-β), thereby weakening the physical stromal barrier and inhibiting pro-cancer signaling." (PMID 41154598, 2025). "FAPI-RGD and FAP-RGD, which dimerize with RGD peptide, exhibit high tumor uptake with favorable distribution." (PMID 40438601, 2025). "Targeting FAP with a radiolabeled FAP inhibitor (FAPI) allows for effective detection and potentially destruction of tumor tissue while minimizing the impact on healthy tissue." (PMID 41463267, 2025). "Early‐generation FAP‐targeted probes, such as FAPI‐04, exhibited limitations for fluorescence imaging due to rapid blood clearance and short tumor retention times." (PMID 40656546, 2025). "FAP-mediated alterations of ECM integrity, TC cells and CAFs underscore its potential as a powerful marker for tumor immunogenicity, immune infiltration and metastasis rendering it a promising therapeutic target for the treatment of aggressive ATC." (PMID 41233863, 2025). "Additionally, NK cells equipped with synthetic receptors targeting stromal components like FAP or integrins may selectively disrupt the tumor stroma while maintaining anti-tumor activity, offering a promising strategy for tackling the complex TME of biliary malignancies." (PMID 40013133, 2025). "To evaluate the effect of tumoral ITGB2 on CAFs within the TME, we measured protein levels of CAF activation markers α‐SMA, FAP, and FSP in tumor tissues using Western blot analysis." (PMID 40071217, 2025). "Agents targeting fibroblast activation protein (FAP), or modulating mechanical properties of the ECM, are being explored to render the stroma less permissive to tumor growth and more supportive of immune infiltration." (PMID 41179287, 2025). "FAP inhibitors, such as talabostat, have demonstrated the ability to disrupt CAF-mediated tumor support, reducing tumor growth and enhancing immune infiltration into the TME." (PMID 40486595, 2025). "Where target antigens are co-expressed by the stroma and tumor (e.g., LRRC15, FAP), prefer payload-delivery strategies if the expression is tumor-dominant, and avoid indiscriminate stromal depletion when the lineage is ambiguous." (PMID 40940809, 2025). "In tumor tissues, SPP1+ macrophages engage in close crosstalk with FAP+ CAFs through specific signaling pathways, resulting in the immunosuppressive niche formation." (PMID 41425545, 2025). "This dysregulated matrix, which correlated with tumour stiffness, was found mainly in areas occupied by alpha-smooth muscle actin-positive (α-SMA +ve) and fibroblast activation protein-positive (FAP +ve) cells, alongside lymphocytes and macrophages." (PMID 40379112, 2025). "Multi-plex IHC confirmed co-localization of RUNX1 with FAP protein at the tumor core and USF2 with PDGFRA expression at the tumor margin." (PMID 39870619, 2025). "Compared with those in CT-26/EV cells, CT-26/FGFR4 tumor-derived CAFs exhibited higher expression levels of CAF markers, such as α-SMA, fibroblast activation protein (FAP), PDGF receptor (PDGFR), and vimentin, at both mRNA and protein levels." (PMID 40447617, 2025). "FAPα is the most common target of choice in anti-CAF therapy due to its expression in the tumor microenvironment and its role in tumor development." (PMID 40918451, 2025). "The results showed that, compared to the control group, MIF knockdown in SCC7 cells resulted in a reduction in tumor size, accompanied by a significant decrease in the number of both CD74+PDGFRB+ and FAP+ cells." (PMID 39891284, 2025). "After cultured for 24 h, proteins of FAP and CD74 were significantly upregulated by the tumor-conditioned medium." (PMID 39891284, 2025). "Moreover, because tumor suppression could be achieved with no weight loss, the data suggest that any FAP-expressing fibroblasts that might have been killed in healthy tissues must have occurred with little overt toxicity." (PMID 40034702, 2025).